IL13 (interleukin 13)
Diseases named in the same sentence as IL13 in open-access papers (continued):
Sharing a sentence is not in itself a finding about the gene and the disease.
cancer (continued). "Despite mAb 5.5.4 partially blocked IL-13 mediated receptor internalization from the cancer cell surface it still promotes receptor degradation." (PMID 33917458, 2021). "This delicate interaction between muscle and cancer cells is accompanied by several processes: an increase in IL-4 and IL-13 secretion, an overexpression of annexin A5 and syncytin 1 and a noticeable fusion of cancer cells." (PMID 33841508, 2021). "Protein tyrosine phosphatase-1B mediates IL-13-induced cancer cell proliferation, migration, and survival via Src activation." (PMID 33450900, 2021). "In an immunohistochemical analysis of CRC patients at stage I–III, high IL-13 and IL-13R expression was seen in 50% (181/359) and 42% (152/359) of the cancers, respectively." (PMID 33450900, 2021). "As a result, CXCL10, IGF1, MMP3, MMP1, ICAM1, and IL-13 levels were markedly up-regulated within NPC samples relative to the non-carcinoma samples (P < 0.05)." (PMID 34544905, 2021). "Both MYC and Twist1 demonstrated binding at multiple sites in the promoter regions of CCL2 and IL13 in the ChIP-seq data from several different cancer cell lines." (PMID 31933479, 2020). "In this report, we discovered the association between IL13Rα2 and the tyrosine phosphatase PTP1B for IL-13 signaling in different cancer types, paving the way to the therapeutic use of PTP1B inhibitors." (PMID 32098194, 2020). "This study showed that higher serum IL-13 levels and higher serum AFP levels were directly associated with cancer (OR = 2.036, 95% CI = 1.384–3.076, p = 0.001) and (OR = 9.151, 95% CI = 2.94–28.425, p < 0.001), respectively." (PMID 32283835, 2020). "IL-13 is generally thought of as a T helper type 2 (Th2) cytokine involved in a variety of disorders, including cancer and inflammatory disease." (PMID 32316187, 2020). "In ovarian cancer (OC), IL-13 was described to regulate cancer invasion and metastasis through IL13Rα2." (PMID 32098194, 2020). "A better understanding of the IL13/IL13Rα2 signaling pathway would facilitate the discovery of novel therapeutic candidates in those cancers characterized by high expression of IL13Rα2, such as colorectal, ovarian, or GBM." (PMID 32098194, 2020). "Scratch assay was used to evaluate the effect of exogenous IL-4 and IL-13 (100 ng/mL) on the migratory properties of cancer cells recorded at 0, 24, 48, and 72 h." (PMID 32512917, 2020). "Both ILs were elevated locally at protein level in all cancers but only IL13 transcripts in colon were upregulated." (PMID 32512917, 2020). "Further, combined MYC and TWIST1 expression correlated strongly with CCL2 and IL13 in the pan-cancer cohort (p=1.4×10−109)." (PMID 31933479, 2020). "After the treatment with IL-13, cancer cells knocked down for PTP1B, showed an increase of IL13Rα2 on the cell surface together with less protein degradation." (PMID 32098194, 2020). "Available literature presents contradicting data concerning effects of IL-4 and IL-13 on cancer cell proliferation and ability to evade pro-apoptotic signals." (PMID 32512917, 2020). "Members of the let-7 family can target inflammatory cytokines, such as IL-6 by let-7a and IL-13 by let-7f, shown to contribute to cancer-cell apoptosis and anti-inflammatory action respectively." (PMID 32716937, 2020). "In CRC, high systemic IL-13 translated into better prognosis and accompanied less advanced cancers in terms of the overall disease stage and lymph node and distant metastases." (PMID 32512917, 2020). "Initially, the IL-13/IL-13Rα2 axis was demonstrated to mediate signaling through AP-1 transcriptional pathway in a number of human cancers." (PMID 32098194, 2020). "To investigate the activity of PTP1B in the pro-invasive and metastatic processes induced by IL-13 in cancer cells, we prepared KM12SM/SW620 CRC cells, U118/U87 GBM cells and A2780/SKOV3 OC cells PTP1B-silenced using two different siRNAs." (PMID 32098194, 2020).
cancer (continued). "Correspondingly, IL13 in clinical samples was inversely related to the expression of GLUT1, the upregulation of which is a hallmark of cancer-related metabolic reprogramming." (PMID 32512917, 2020). "The role of IL-4 and IL-13 in leukocyte biology and hematological malignancies is well established and their involvement in activation of cancer-promoting macrophages and myeloid-derived suppressor cells is increasingly being recognized." (PMID 32512917, 2020). "This study found a significant contribution of IL-13 rs20541, IL-13R2 rs5946040, and PD-L1 rs2282055 at univariate analysis with cancer progression in NASH." (PMID 32283835, 2020). "We uncovered the relevance of PTP1B-mediated Src activation for IL-13 signaling through IL13Rα2 in multiple types of cancer." (PMID 32098194, 2020). "Together, MYC and Twist1 induce the cancer cell to secrete cytokines like Ccl2 and Il13 that lead to recruitment and polarization of macrophages respectively, thus causing metastasis." (PMID 31933479, 2020). "This revealed that patients that had higher levels of MYC and TWIST1 proteins in their tumors also had increased levels of CCL2 and IL13, more activated macrophages and were less likely to recover from their cancer." (PMID 31933479, 2020). "This case‐control study of 693 newly‐diagnosed BC cases and 714 cancer‐free controls evaluated the effect of multiple exposures to environmental factors and polymorphisms in CYP27B1 and IL‐13 on BC risk." (PMID 31041852, 2019). "IL4 and IL13 bind to their receptors specifically, and both cytokines can have effects on cancer cells expressing appropriate receptors." (PMID 31540495, 2019). "In these models, IL-13 mediated cancer invasion and metastasis through IL-13Rα2 and signaling via AP-1/ERK pathway." (PMID 30572904, 2018). "Our previous studies on pancreatic ductal adenocarcinoma mouse model of human cancer suggested that IL-13 can mediate AP-1 signaling in IL-13Rα2 positive tumors." (PMID 30572904, 2018). "A report has illustrated that high systemic levels of IL-13 are related to the increases in the occurrence of different cancers." (PMID 30643796, 2018). "This property of receptor sharing for IL-4 and IL-13 has also been observed in other cancer cell lines." (PMID 28752098, 2017). "The expressions of IL-4, IL-10 and IL-13 were significantly decreased in the metformin-treated cancer cells compared to the control cells." (PMID 28157701, 2017). "M2 type macrophages, one type of inflammatory cells that are differentiated by IL-4 and IL-13 stimulations, are known as major mediators linking cancer and inflammation." (PMID 26790618, 2016). "Further characterization of the functional and mechanistic relationship between IL-13 and other inflammatory factors in cancer progression remains to be explored." (PMID 27533463, 2016). "Mast cells play a key role in the pathogenesis of cardiovascular diseasesand cancers via secreting a variety of cytokines includingTNF-α, IL-3, IL-4, IL-5, IL-6, IL-10, IL-13, IL-14 and IL-16." (PMID 26625310, 2016). "In the past few years, more and more attention has been drawn to the research on the connection of IL-13 and cancer metastasis." (PMID 27533463, 2016). "The data presented here, showing a protective role for IL-13 in different models of epithelial carcinogenesis, provides new perspective to further studies on the links between atopy and cancer." (PMID 27357235, 2016). "Immunotoxin therapy by IL-13-PE will essentially target cancer cells that upregulate IL-13Rα2 and will therefore select against its expression." (PMID 23421960, 2013). "As an anti-cancer strategy, IL-13-PE immunotoxin treatment has already proven to be efficacious against tumors in many cancer mouse models and is currently being used in clinical trials." (PMID 23421960, 2013).
cancer (continued). "Primary cultures were derived from the tumors of the Tgfbr1/Pten 2cKO mice to determine if the upregulated expression of IL-13Rα2 by the cancer cells would make them sensitive to the IL-13-PE cytotoxicity." (PMID 23421960, 2013). "Since IL-13Rα2 binds to IL-13 with high affinity and then undergoes internalization, expression of this receptor can thereby be targeted for delivery of a bacterial toxin into a cancer cell." (PMID 23421960, 2013). "We found that a recombinant IL-13-PE immunotoxin targeting IL-13Rα2 has remarkable anti-cancer activity against these tumors." (PMID 23421960, 2013). "MMP-9 was decreased in fibroblast cultures exposed to IL-13, but in tissue extracts there was a general increase in all groups compared to cancer controls." (PMID 23300643, 2012). "In tissue extracts by qPCR, IL-13 mRNA was increased in fibrotic CD muscle, and this was significant compared to cancer (p<0.05)." (PMID 23300643, 2012). "We next examined the enhancement of the anti-cancer effect of IL-13-PE by HDAC inhibition in xenograft mouse models of human cancer." (PMID 21477288, 2011). "Interleukin-13 Receptor α2 (IL-13Rα2) is a high affinity receptor for the Th2 derived cytokine IL-13 and a known cancer testis antigen." (PMID 21477288, 2011). "The anti-cancer effect of IL-13-PE was evaluated using a protein synthesis inhibition assay in vitro." (PMID 21477288, 2011). "Interleukin 13 (IL-13) is another cytokine with anti-inflammatory activity, produced by T cells, that plays an important role in many biological activities, including cancer onset." (PMID 19384429, 2007). "This property of sharing of receptors for IL-4 and IL-13 has also been observed in other cancer cell lines and thus appears to be universal." (PMID 11870521, 2002). "Additionally, cytokines namely IL-4 and IL-13, secreted by Th2 cells, promote cancer progression by inducing polarization of M2 macrophages." (PMID 39726600, 2024). "The impact of IL-13 on cancer is complex and not fully understood." (PMID 39132165, 2024). "IL-13 concentrations have been previously measured in cancer patients." (PMID 39272892, 2024). "In addition, IL-13 promotes the biosynthesis of cytidine deaminase in colonic epithelial cells, conferring the potential to activate the inflammatory-cancer transition in the intestine." (PMID 37534250, 2023). "In addition, it’s well known that Th2 cells contribute to cancer progression and metastasis by secreting IL-4, IL-5, IL-10 and IL-13." (PMID 37950236, 2023). "In addition, STAT6 negatively regulates Dvl2 levels and restrains cancer cell colony formation by interleukin- 13 (IL-13)." (PMID 36766788, 2023). "IL-13 may also directly promote cancer cell proliferation and metastasis through an alternative IL-13Rα2 for example in pancreatic cancer." (PMID 37455828, 2023). "In addition to low affinity receptors, IL-13 also binds to high affinity receptors such as IL13Rα2 in cancer cells." (PMID 35612318, 2022). "IL-4 and IL-13, secreted by activated Th2 cells, induce aberrant expression of activation-induced cytidine deaminase (AID), which can result in DNA mutations with potential cancer development." (PMID 34986892, 2022). "Moreover, decreased levels of IFN-γ, GM-CSF, IL-1β, IL-7, IL-12, and IL-13 secretion were seen in cancer patients’ peripheral-blood derived sera when compared to those from the healthy individuals." (PMID 35203349, 2022). "Cancer-associated fibroblasts (CAFs) can inhibit both the innate and adaptive antitumor immune response by secreting numerous chemokines and cytokines, such as TGF-β, IL-6, IL-8, IL-13, CXCL12, CXCL14, and VEGFA." (PMID 35646893, 2022). "IL13 frequently accompanies mitochondria-related conditions, including in infectious disease, inflammatory diseases, and metabolic diseases and even in cancers." (PMID 36497047, 2022). "Mitochondrial oxidative stress in cancer cells has been indicated to induce an increase in IL13." (PMID 36497047, 2022).
cancer (continued). "Through several mechanisms, IL-13 promotes and combats cancer progression." (PMID 34048465, 2021). "From our multivariate regression model in the post-C/T group, the finding that higher IL-13 predicted worse SFT may suggest impaired executive function after cancer or chemotherapy." (PMID 34073990, 2021). "In addition, IL-13 appears to play its own distinct role in cancer cells through binding to IL-13Rα2 with high affinity and mediating invasion and metastasis via IL-13Rα2, ERK/activator protein 1 (AP-1) signaling, and matrix metalloproteinases (MMPs) pathways." (PMID 33804263, 2021). "Furthermore, a research involving 241 CRC patients found that serum IL-13 levels were significantly lower in advanced cancer patients, and lower serum IL-13 levels were significantly associated with a poorer prognosis." (PMID 35003085, 2021). "More and more evidence has been provided in recent years that interleukin-4 (IL-4), interleukin-13 (IL-13), and their receptors play an important role in cancer cell proliferation and other biological behaviors, such as migration and invasion enhancing the malignant phenotype." (PMID 33450900, 2021). "However, the results of some studies indicate a contradictory role for IL-13 in promoting and fighting the progression of cancer." (PMID 33343662, 2020). "Inhibiting two cytokines known as CCL2 and IL13 prevented the cancer cells from moving." (PMID 31933479, 2020). "The use of IL-13 inhibitors in targeted immunotherapy in cancers is also being considered." (PMID 33343662, 2020). "This study provides evidence for the first time that PTP1B mediates IL13Rα2 pro-tumorigenic activities in the three types of cancer and may provide a novel therapeutic target to inhibit IL13/IL13Rα2 signaling." (PMID 32098194, 2020). "Correlation of MYC+TWIST1 expression with CCL2 and IL13 in TCGA pan-cancer cohort (n = 9502)." (PMID 31933479, 2020). "Interestingly, this study found that higher serum IL-13 levels and higher serum AFP levels were associated with cancer (OR = 1.625, 95% CI = 1.077–2.451, p = 0.021) and (OR = 8.231, 95% CI = 2.668–25.394, p < 0.001) respectively." (PMID 32283835, 2020). "Both IL-13 promoted a similar pro-invasive capacity on human cancer cells." (PMID 32098194, 2020). "Available literature on IL-13 in the GIT cancers is even scantier than that concerning IL-4." (PMID 32512917, 2020). "IL4 and IL13 bind to IL4Rα and IL13Rα1 chains, forming functional structures in cancer cells." (PMID 31540495, 2019). "There are data on IL-13 promoter polymorphisms as well as IL-13 serum levels in a variety of cancer entities of various stages, but no clear causality patterns have emerged to date." (PMID 30759882, 2019). "Conversely, IL-13-producing ILC2s also show protumor immunity and are associated with a negative outcome in cancer." (PMID 32117199, 2019). "Furthermore, metformin treated cancer cells displayed inhibited secretion of IL-4, IL-10 and IL-13; cytokines important for inducing M2 macrophages." (PMID 28157701, 2017). "It is well known that IL-4 and IL-13 play an important role in cancer development." (PMID 28893247, 2017). "By contrast, cancer cell EVs decreased the level of IL-13, an anti-inflammatory cytokine." (PMID 28947958, 2017). "As IL-13R is expressed in many cancers, IL-13 immunotoxins including IL-13PE were developed." (PMID 27351230, 2016). "Multiple mechanisms seem to be operational in IL-13-induced cancer invasion and metastasis." (PMID 27533463, 2016). "IL-13 is known to regulate cancer invasion and metastasis in different cancers." (PMID 26500775, 2015). "It is possible that some of these, such as the orphan chemokine CXCL17, recently shown to promote angiogenesis and cancer progression, could also be involved in regulating metastatic dissemination via the IL-13 pathway." (PMID 26208975, 2015).
cancer (continued). "Interestingly, the role of IL-13, a key regulator in innate immunity, remains contested in cancer as it may exhibit either pro- or anti-tumorigenic effects depending on context." (PMID 39623404, 2024). "However, it is found that the classical type 2 immune cytokines IL-4, IL-5, IL-9, and IL-13 may have conflicting roles in cancer." (PMID 37455828, 2023). "Thus, not only the distinct expression levels of respective receptor chains, but also the ratio between IL-13Rα1 and IL-4Rα expression may be crucial for the effect of IL-4 and IL-13 on the cancer cell phenotype." (PMID 35409019, 2022). "Furthermore, IL-4/IL-13 has been shown to contribute to cancer growth and metastasis." (PMID 36159866, 2022). "Nevertheless, down-regulation of IL-13Rα2 or targeting IL-13Rα2 by receptor targeted immunotherapeutic agents, such as IL-13-PE, IL-13Rα2 cancer vaccines or adoptive transfer of chimeric antigen receptor modified T cells targeting IL-13Rα2, may improve the prognosis of patients with PDAC." (PMID 32443847, 2020). "Along with cancer progression, following the “equilibrium” and “escape” phases of cancer immune-editing, tumor microenvironment elicits the alternative, M2, activation of TAMs, induced by the secretion of cytokines, such as IL-4 and IL-13, by Th2 cells, basophils, and eosinophils." (PMID 32650452, 2020). "The production of IL-13 by ILC2s is associated with a negative outcome in cancer." (PMID 31024531, 2019). "Since IL-13 producing type II NKT have been associated with immune suppression mediated via MDSC-derived TGF-β, combining NKT based therapies with chemotherapeutics might reverse the flavor of NKT in this case from “bad” to “good” in terms of cancer control." (PMID 30298063, 2018). "We have previously demonstrated that IL-13Rα2 is an excellent target for various immunotherapy approaches such as IL-13 immunotoxin, IL-13Rα2 cDNA vaccine and combination of both which mediates significant efficacy and increased overall survival in animal models of human cancer." (PMID 30572904, 2018). "Indeed, this receptor has been shown to mediate IL-13 signaling in cancer cells." (PMID 29168083, 2018). "To date, it remains unclear whether TMEM16A can be regulated by IL-4 and IL-13 in cancer cells." (PMID 28893247, 2017). "However, the function and mechanism of IL-13 in cancer EMT and aggressiveness are still unknown now." (PMID 27533463, 2016). "Therefore, the fact that depletion of STAT6 impaired TP63 upregulation suggests that a STAT6-TP63 axis may be involved, at least in part, in IL-13-mediated suppression of cancer cell migration, extravasation, and eventually metastasis." (PMID 26208975, 2015). "Treatment with IL-13-PE at an early time point in cancer development may have selectively hindered the growth and establishment of high IL-13Rα2 expressing cancer cells in the mice, resulting in the formation of tumors with decreased overall expression of this receptor." (PMID 23421960, 2013). "In particular, ILC2s are mostly defined as a protumorigenic subset, given their type-2 immune functions through the secretion of IL-13, IL-5, IL-9, and the epidermal growth factor AREG, which has a detrimental role in various types of cancer." (PMID 40247153, 2025). "Logistic regression analysis has identified salivary IL-13 and TGF-β as independent factors for cancer cachexia." (PMID 39272892, 2024). "In this analysis, we demonstrated saliva as a valuable specimen for cachexia investigation and established IL-13 and TGF-β as potential cancer cachexia biomarkers." (PMID 39272892, 2024). "Both examples support using saliva as a sample that offers insight into the systemic metabolic condition of cancer cachexia and provides new information about the concentration of potential biomarkers TGF-β and IL-13." (PMID 39272892, 2024).